PTCH1 (patched 1)
Diseases named in the same sentence as PTCH1 in open-access papers (continued):
Sharing a sentence is not in itself a finding about the gene and the disease.
Gorlin syndrome (continued). "As the p.S1132P mutation of PTCH1 was reported to be causative for NBCCS, we concluded that this alteration was responsible for Gorlin syndrome in family C." (PMID 26544948, 2015). "Despite exhaustive analysis, PTCH1 mutations are often unidentifiable in some patients; for example, Sanger sequencing of PTCH1 exons 2–23, encompassing the entire coding region, detected mutations in approximately 40%–70% of individuals with a typical clinical presentation of Gorlin syndrome." (PMID 26544948, 2015). "Mutations in PTCH1 can cause the development of nevoid basal cell carcinoma syndrome (NBCCS), also known as Gorlin syndrome." (PMID 24163262, 2013). "Tumours in heterozygous Ptch1 mice exhibited elevated transcript levels of Gli1 and Ptch1 itself, indicating that abnormal Hedgehog signalling may be common to the various tumours associated with Gorlin's syndrome." (PMID 22550422, 2012). "The Ptch1 heterozygous (Ptch1+/−) mouse is an established model of human Gorlin syndrome that is sensitive to the carcinogenic effect of ionizing radiation." (PMID 41007286, 2025). "Heterozygous mutations in PTCH1 (patched 1) have been identified in patients with Gorlin syndrome, also known as basal cell nevus syndrome 1 (BCNS1, OMIM #109400), and holoprosencephaly 7 (HPE7, OMIM #610828)." (PMID 38884091, 2024). "BCC malignancy spectrum is variable and complex, and it can appear spontaneously or through predisposing genetic syndromes, such as the Nevoid basal cell carcinoma syndrome (NBCCS), due to PTCH1 gene variants." (PMID 38287479, 2024). "One of the models exhibited somatic loss of heterozygosity of the PTCH1 wild-type allele, recapitulating the development of the SHH subgroup of medulloblastoma seen in patients with Gorlin syndrome carrying PTCH1 germline mutations." (PMID 36831595, 2023). "Gorlin–Goltz syndrome, also known as nevoid basal cell carcinoma syndrome (NBCCS), is an autosomal dominant illness characterized by multisystemic developmental defects caused bypathogenic variants such as patched-1(PTCH1) gene and/or SUFU gene variants." (PMID 37564720, 2023). "The gene panel analyzed the PTCH1, PTCH2, SUFU, and SMO genes, all of which are associated with Gorlin syndrome." (PMID 37762102, 2023). "They reported the presence of simultaneous mutations in PTCH1 and PTCH2 in patients with Gorlin syndrome." (PMID 37762102, 2023). "Recent studies have identified pathogenic mutations in the hedgehog pathway, especially in “patched” (PTCH1 and PTCH2) genes, in Gorlin syndrome." (PMID 37887561, 2023). "Germline inactivation of one copy of the Hh receptor Patched 1 (PTCH1) gene and, more rarely, of PTCH2, or of Suppressor of Fused (SUFU), followed by the somatic loss of the second allele results in Gorlin syndrome that are frequently observed in BCC patients." (PMID 35804983, 2022). "Gorlin-Goltz syndrome, eponymous for the nevoid basal cell carcinoma syndrome (NBCCS), is a rare genodermatosis, with an autosomal dominant transmission, due to PTCH1 germline mutations." (PMID 35775005, 2022). "Gorlin syndrome (MIM 109,400), a cancer predisposition syndrome related to a constitutional pathogenic variation (PV) of a gene in the Sonic Hedgehog pathway (PTCH1 or SUFU), is associated with a broad spectrum of benign and malignant tumors." (PMID 33860896, 2021). "Patient characteristics for the Gorlin M0 Cohort (all genetically diagnosed PTCH1 and SUFU associated Gorlin syndrome patients) vs. the Comparative M0 Cohort (all medulloblastomas (MB), SHH+, M0, <4y)." (PMID 34888241, 2021). "Activating or loss of function mutations in the HH pathway genes SMO and PTCH1 occur in human gastric tumors, sporadic BCC, medulloblastoma, nevoid basal cell carcinoma syndrome (NBCCS), and colorectal cancer." (PMID 33494284, 2021). "In fact, there are no clinical reports available on the identification of genes other than PTCH1 that drive the development of BCC in patients with Gorlin syndrome." (PMID 34674729, 2021).
Gorlin syndrome (continued). "Patient characteristics for the Gorlin cohort (all genetically diagnosed PTCH1 and SUFU associated Gorlin syndrome patients) vs. the Comparative cohort (all DMB/MBEN, SHH+, <3.5y)." (PMID 34888241, 2021). "Previously, studies suggested that both PTCH1 and PTCH2 are causative genes of Gorlin syndrome and holoprosencephaly." (PMID 32864857, 2020). "Similar to PTCH1- and SUFU-associated MBSHH in Gorlin syndrome, patients in this study were typically diagnosed with MB during infancy." (PMID 31609649, 2020). "Misexpression of MYCN in both otherwise-normal NES cells and PTCH1+/− NES cells derived from patients with Gorlin syndrome each generated medulloblastoma in mice." (PMID 31204176, 2019). "In the case of the HH pathway, the target was uncovered as a result of the gene mapping studies, demonstrating that basal cell nevus carcinoma syndrome (BCNS), also known as Gorlin syndrome, is a consequence of mutations in Patched-1 (PTCH1), the receptor for HH ligands." (PMID 30068568, 2018). "Causative mutations in several genes associated with the sonic hedgehog (SHH) signaling pathway, including PTCH1, have been identified in Gorlin syndrome patients." (PMID 29088246, 2017). "Aberrations in Hh pathway genes PTCH1, PTCH2, and SUFU are associated with nevoid basal cell carcinoma syndrome (NBCCS; also known as Gorlin syndrome), which predisposes patients to SHH-MB, basal cell carcinoma, and skeletal abnormalities." (PMID 29050204, 2017). "We previously performed whole exome and targeted re-sequencing of 58 sporadic and Gorlin’s Syndrome BCC samples and found expected mutations in PTCH1 and SMO in accordance with our previous publications." (PMID 28030567, 2016). "There is a consistent predisposition to PTCH1 or SUFU germline mutations in MB patients aged < 3 years, with MBEN strongly related to Gorlin’s syndrome." (PMID 26857864, 2016). "When PTCH1 binds to the soluble ligand sonic hedgehog (SHH)—or inactivated by loss-of-function mutation, as in Gorlin’s syndrome—this inhibition on SMO is withdrawn and the pathway is turned on." (PMID 25775002, 2015). "Mice with Ptch1 knocked out or with expression of oncogenic SmoM2 develop tumors similar to Gorlin syndrome patients, BCCs and medulloblastomas." (PMID 26343727, 2015). "Germline deletions affecting the PTCH1 gene is responsible for the Gorlin syndrome phenotype also known as Nevoid Basal Cell Carcinoma Syndrome (NBCCS)." (PMID 25184114, 2014). "Most associate with Gorlin syndrome or nevoid basal cell carcinoma syndrome (NBCCS, MIM #109400) due to haploinsufficiency of the PTCH1 gene (MIM *601309)." (PMID 21693067, 2011). "Most of them, however, span the PTCH1 gene (MIM *601309) and associate with Gorlin syndrome or nevoid basal cell carcinoma (NBCCS, MIM #109400) due to haploinsufficiency of PTCH1." (PMID 21693067, 2011). "Our systematic review excluded Gorlin syndrome, a hereditary cancer syndrome predominantly involving PTCH1 mutations, to avoid skewing the results for non-Gorlin BCC patients." (PMID 40522768, 2025). "The patient subsequently tested negative for germline variants of PTCH-1, alterations of which have been reported in cases of nevoid basal cell carcinoma syndrome (NBCCS), fetal rhabdomyoma, as well as rhabdomyosarcoma." (PMID 40310147, 2025). "Background and Clinical Significance: Basal cell nevoid carcinoma syndrome, or Gorlin–Goltz Syndrome (GGS), is a genetic disease caused by germline mutations in genes involved in the Sonic HedgeHog (SHH) signaling pathway, mainly in the PTCH1 gene." (PMID 40729247, 2025).
Gorlin syndrome (continued). "We also screened 27 PTCH1/SUFU pathogenic variant-negative patients with Gorlin syndrome for GPR161 and found no suspicious variants." (PMID 36961676, 2023). "Bholah and collages demonstrated the importance of comprehensive transcript mutation analysis for individuals with clinically diagnosed Gorlin syndrome when PTCH1 variants have not been detected by genomic sequencing or by copy number analysis." (PMID 37504252, 2023). "Our specific screen of GPR161 in our cohort of 27 PTCH1/SUFU pathogenic variant-negative patients with Gorlin syndrome found no pathogenic or likely pathogenic variants." (PMID 36961676, 2023). "Interestingly, germline mutations in SUFU, PTCH1, and GPR161 have been observed in heritable predisposition to MB, such as Gorlin syndrome." (PMID 37510333, 2023). "P504 has direct interactions with the ligand and it is involved in all interaction sites of the SSD, and the mutant PTCH1-P504L may result in Gorlin syndrome." (PMID 35187087, 2022). "Instead, a frameshift mutation NM_000264.3:c.2757_2758delCT (p.Phe919Leufs*39) in PTCH1 was found, suggesting basal cell nevus syndrome rather than TS." (PMID 35562572, 2022). "The best-known condition is represented by the Basal Cell Nevus Syndrome (BCNS or Gorlin–Goltz syndrome), an autosomal-dominant disorder primarily caused by mutations in the PATCHED-1 (PTCH1) gene, leading to the inappropriate activation of the Hedgehog signaling pathway." (PMID 35804983, 2022). "One male patient met four of the major criteria of the Gorlin syndrome, with the existence of PTCH1 and PTCH2 mutations in his normal oral tissue." (PMID 34674729, 2021). "In patients with Gorlin syndrome, mutations are found in PTCH1, the driver gene for non-syndromic BCC." (PMID 34674729, 2021). "Despite the lack of evidence of a loss of function of PTCH1 protein, this mutation was reported once to be associated with a Gorlin syndrome (dbSNP: rs1588610385)." (PMID 34409296, 2021). "In rare cases, germline variants in the PTCH1, PTCH2, SUFU genes may be responsible for an inherited form of BCC known as Gorlin Syndrome (MIM # 109400)." (PMID 34284772, 2021). "One of the medulloblastomas showed loss of heterozygosity in the PTCH1 gene while the benign teratoma, i.e. the non-medulloblastoma portion, did not, indicating a close clinical correlation between tumorigenesis in Gorlin syndrome patients and Gln-iPSCs." (PMID 32436863, 2020). "The aberrant activation of HH pathway has been first related to malignant transformation in the context of Gorlin–Goltz syndrome, also called nevoid basal cell carcinoma syndrome (NBCCS), an autosomal dominant disorder characterized by basal cell carcinomas due to the mutation of PTCH1." (PMID 32033196, 2020). "Notably, the Ptch1 knock-out mouse model develops tumors similar to Gorlin syndrome patients, like BCC, MBs, and sporadic rhabdomyosarcomas, providing evidence about the driver role of Hh signaling for cancer development." (PMID 31552081, 2019). "Its related syndrome, basal cell nevus syndrome (BCNS), is characterized by skeletal abnormalities, jaw keratocysts, and calcification of brain structures in addition to carcinoma, and mutations in the Ptch1/2 and SuFu genes have been found in BCNS patients." (PMID 31781166, 2019). "The brothers were diagnosed as sporadic cases of Gorlin syndrome, because their parents do not have the constitutive PTCH1 mutation." (PMID 29498494, 2018). "Neither founder mutations nor hot spot locations have been described for PTCH1 in Gorlin syndrome patients." (PMID 29498494, 2018). "In this study, we first used NGS to screen PTCH1 genes in four individuals with Gorlin syndrome." (PMID 28915250, 2017). "Moreover, patients with Gorlin syndrome (basal-cell nevus syndrome), an autosomal rare condition where one copy of PTCH1 gene is missing are prone to developing BCC and medulloblastoma." (PMID 27486983, 2016).
Gorlin syndrome (continued). "In summary, we systematically screened individuals with familial Gorlin syndrome for causative genetic alterations using hybridization and PCR-based NGS, and found that various PTCH1 mutations, including large deletions, could explain the disease phenotypes." (PMID 26544948, 2015). "In addition, mutations in rare causative genes other than PTCH1, such as PTCH2 and SUFU, have also been detected in individuals suffering from Gorlin syndrome." (PMID 26544948, 2015). "Despite reports of numerous germline PTCH1 mutations in patients with Gorlin syndrome, no clustering of mutations has been identified." (PMID 26544948, 2015). "Significant progress in gaining knowledge about Hh signaling in human cancers was achieved by the discovery that mutations of the human homolog of the Drosophila patched gene (PTCH1) are associated with a rare hereditary form of BCC (basal cell nevus syndrome, also called Gorlin syndrome)." (PMID 23303278, 2013). "Importantly, it highlights the possibility that low-level PTCH1 mosaicism may still result in a classic Gorlin syndrome phenotype." (PMID 41888819, 2026). "Therefore, it is reasonably assumed that the mutation analysis of genes other than PTCH1 using WES may define potential diagnostic, preventive, and therapeutic opportunities for Gorlin syndrome and illuminate disease mechanisms." (PMID 28915250, 2017). "Causative mutations in several genes associated with the sonic hedgehog (SHH) signaling pathway, including PTCH1, PTCH2, and SUFU, have been identified in Gorlin syndrome patients." (PMID 29088246, 2017). "In sporadic, but not Gorlin syndrome-related BCCs, the biallelic inactivation of PTCH1 is identified in about 30% of patients." (PMID 37887561, 2023). "We did not identify GPR161 in 27 PTCH1/SUFU negative Gorlin syndrome families which represent all the 27/86-(31.4%) unexplained by known genes (59 were due to PTCH1/SUFU) meaning an unexplained population frequency far lower at 0.0021% (1 in 46,400)." (PMID 36961676, 2023). "Gorlin syndrome is characterized by genetic abnormalities in negative regulator molecules in the Hh pathway, most frequently PTCH1 and, rarely, PTCH2 and SUFU." (PMID 37629084, 2023). "However, the presence of driver genes other than the PTCH1 in Gorlin syndrome has not been explored." (PMID 34674729, 2021). "However, since the deletion in this patient was distal to the PTCH1 gene, this newborn girl did not have Gorlin syndrome." (PMID 27516809, 2016). "These genes have not (yet) been implemented in routine genetic testing strategies for patients with the suspected diagnosis of Gorlin syndrome and might (partially) close the diagnostic gap in young children with SHH-activated medulloblastomas lacking germline PTCH1 or SUFU mutations." (PMID 34888241, 2021). "Testing for PTCH1 and SUFU was negative, which reduced the likelihood of Gorlin syndrome or other known BCC syndromes." (PMID 40290801, 2025).
medulloblastoma (187 papers, 2008 to 2026). A malignant, invasive embryonal neoplasm arising from the cerebellum. "In the medulloblastoma, we observed 45 tumor‐specific pathogenic variants in 35 CNS tumor‐related genes, including PTCH1, PTCH2, and SMO, which are frequently altered in medulloblastomas." (PMID 40880425, 2025). "Ligand-independent pathway activation results from mutations in the Hedgehog pathway components, including PTCH1, which has been correlated with basal cell carcinoma, medulloblastoma, and several other types of cancer." (PMID 41353440, 2025). "Loss-of-function mutations of PTCH1/2 result in aberrant activation of Hedgehog signal pathway, and are driver oncogenic mutations in some tumor types, including basal cell carcinoma, medulloblastoma and rhabdomyosarcoma." (PMID 39389955, 2024). "Loss-of-function mutations in PTCH1 are associated with altered neuronal development and the malignant brain tumour medulloblastoma." (PMID 38411252, 2024). "Affected individuals with this variant have a significantly higher risk of medulloblastoma in early childhood of 33% compared to affected individuals with the PTCH1 variant with a risk less than 2%." (PMID 37408081, 2023). "Further genetic anomalies in Gorlin NES cells, including mutations in DDX3X and GSE1 genes, accelerated tumorigenesis and demonstrated cooperativity among these genes and PTCH1, further elaborating on the genetic causation of medulloblastoma." (PMID 36831595, 2023). "The SHh signaling pathway, which is continuously activated due to inactivation mutations in the PTCH1 gene, is commonly observed in basal cell carcinoma and medulloblastoma." (PMID 37533228, 2023). "This pathway first became associated with medulloblastoma when germline mutations in PTCH1 were found in Gorlin syndrome." (PMID 37943476, 2023). "Individuals with an SUFU pathogenic mutation (33%) have a much higher occurrence of medulloblastoma than those with a PTCH1 pathogenic variant (2%)." (PMID 37629084, 2023). "In SHH medulloblastoma, there is a constitutive activation of hedgehog signaling, often due to inactivating mutations of PTCH1." (PMID 38132264, 2023). "In human medulloblastoma, mutations in PTCH1, SMO, and SUFU, and amplifications of SHH, GLI2, and MYCN, a pathway target gene, have been identified." (PMID 36010600, 2022). "Our results, therefore, supported that PTCH1-related NBCCS patients have a relatively low risk for medulloblastoma." (PMID 33441926, 2021). "Conditional deletion of PTCH1 in cerebellar granule cell precursors (Math1) caused medulloblastoma formation with 100% penetrance." (PMID 34436033, 2021). "The risk of developing medulloblastoma is substantially higher in individuals with SUFU mutations (33%) than in those with PTCH1/2 pathogenic variants (<2%)." (PMID 35096710, 2021). "iPS-derived neural stem cells generated from Gorlin syndrome patients, who are carrying a germline mutation in PTCH1 and are predisposed to medulloblastoma, were transplanted into mouse cerebellum." (PMID 33869004, 2021). "Like BCCs, most Shh-medulloblastomas are characterized by mutations in the PTCH1 gene, and to a smaller extent, in SUFU and SMO genes." (PMID 34572373, 2021). "This is in concordance with previous studies hinting at a reduced PFS and OS for SUFU mutated patients compared to PTCH1 mutated patients or SHH activated DMB/MBEN medulloblastoma patients in general." (PMID 34888241, 2021). "In a previous study, the risk for medulloblastoma was higher in SUFU-related NBCCS cases than in PTCH1-related NBCCS patients." (PMID 33441926, 2021). "In patients with PTCH1 PVs in whom the risk of medulloblastoma is probably under 2%, the need for screening for medulloblastoma is not obvious." (PMID 33860896, 2021). "Medulloblastomas occur significantly more often in patients with pathogenic SUFU variants (33%) than in those harboring PTCH1 variants (<2%)." (PMID 34888241, 2021).